DPP4 (dipeptidyl peptidase 4)
Diseases named in the same sentence as DPP4 in open-access papers (continued):
Sharing a sentence is not in itself a finding about the gene and the disease.
diabetes (continued). "Alogliptin is an oral drug for Type 2 diabetes mellitus that works by inhibiting dipeptidyl peptidase 4 (DPP-4)." (PMID 33451337, 2021). "Identify which species performed most similarly to humans in response to DPP4 inhibitors treatment, regarding standard diabetes diagnosis parameters, namely fasting glucose and HbA1c levels." (PMID 33669354, 2021). "The Consensus of the American Diabetes Association (ADA) and European Association for the Study of Diabetes (EASD) recommends GLP-1RA and DPP-4 inhibitors as therapeutics for T2DM treatment." (PMID 33503878, 2021). "Dipeptidyl peptidase-4 inhibitors (DPP-4i) provide a unique antihyperglycemic effect by regulating incretin peptides in type 2 diabetes mellitus (T2DM) patients who are inadequately controlled with insulin therapy." (PMID 34446063, 2021). "For the evaluation of DPP4 inhibitors, animals such as KKAy and ICR treated with streptozotocin and HFD to induce mild diabetes were used as DPP4 inhibitors improves glucose tolerance and insulin sensitivity in these mild diabetes models." (PMID 34373487, 2021). "Dipeptidylpeptidase-4 (DPP-4) inhibitors, including linagliptin, alogliptin, saxagliptin, sitagliptin, and vildagliptin, are used for the treatment of type 2 diabetes mellitus (T2DM) patients in China." (PMID 34484112, 2021). "Dipeptidyl peptidase-4 inhibitors (DPP-4i) are currently recommended by the AACE as first-line hypoglycemic drugs in type 2 diabetes mellitus (T2DM)." (PMID 34123848, 2021). "Clearly, DPP4 inhibitors are considered to be advantageous for individuals with diabetes and dyslipidemia." (PMID 34489872, 2021). "In specific, genus Anaerotruncus was reported related to hypertension, diabetes mellitus, and dipeptidyl peptidase 4 inhibitors used, which were unbalance in the pre-matched cohort." (PMID 33809103, 2021). "Of all patients receiving treatment for diabetes in 2016, 22% were using dipeptidyl peptidase-4 (DPP-4) inhibitors." (PMID 34256874, 2021). "DPP-4 inhibitors, which are used as diabetes drugs, block the enzymatic activity of DPP-4, therefore inhibiting degradation of the incretin hormones responsible for stimulating insulin secretion as a means of controlling blood glucose level." (PMID 34205264, 2021). "Pharmacological DPP4 inhibitors are now frequently prescribed for glycemic control in patients with type 2 diabetes mellitus." (PMID 33538983, 2021). "Dipeptidyl peptidase-4 (DPP-4) inhibitors can lower blood glucose and reduce cardiovascular risk in patients with type 2 diabetes mellitus." (PMID 33628388, 2021). "Elevated circulatory DPP4 levels and activity have been found in a wide spectrum of metabolic syndromes, including diabetes, obesity, cardiovascular diseases, and nonalcoholic fatty liver diseases." (PMID 33614513, 2021). "Dipeptidyl peptidase-4 (DPP4) inhibitors, an emerging drug for the treatment of diabetes, have been found to have renoprotective effects in addition to glucose-lowering effects and therefore have the potential to be a treatment modality for DKD." (PMID 34950037, 2021). "Trelagliptin is a long-acting selective inhibitor of DPP-4, developed by Takeda pharmaceuticals for the treatment of type 2 diabetes mellitus." (PMID 33734011, 2021). "DPP-4 inhibitors were the most frequently used newer diabetes drugs whereas use of SGLT-2 inhibitors and thiazolidinediones was minimal." (PMID 34911481, 2021). "Although the reported effects of DPP‐4 on COVID‐19 patients with diabetes are controversial, these studies mainly focus on the mortality and did not assess the potential effects of DPP‐4 inhibitors on cardiovascular injury in COVID‐19 patients." (PMID 32713161, 2020). "This study aimed to assess the outcomes of adding basal insulin compared with thiazolidinediones (TZDs) or dipeptidyl peptidase-4 inhibitors (DPP-4is) as a third antidiabetic agent in patients with type 2 diabetes mellitus (T2DM)." (PMID 32238842, 2020).
diabetes (continued). "Since MERS-CoV binds to DPP4, a transgenic mouse model expressing human DPP4 on relevant cells as epithelial and alveolar pulmonary cells has been used to study the impact of diabetes on MERS-CoV infection." (PMID 32848769, 2020). "These patients had a diabetes duration from 4 to 10 years, were all under metformin and dipeptidyl peptidase-4 inhibitors (DPP4-i) and one was also under a sulfonylurea." (PMID 33292447, 2020). "DPP-4 inhibitors are scientifically proven to prolong the incretin effect for the successful treatment of diabetes mellitus." (PMID 32075130, 2020). "Recently, DPP-4 (dipeptidyl peptidase-4) inhibitors have become attractive oral anti-hyperglycemic agents to reduce the pathology of diabetes." (PMID 32075130, 2020). "In univariable regression analysis, a negative correlation between serum total magnesium concentrations and age, diabetes duration, BMI, HbA1c, use of metformin, sulfonylurea derivatives, DPP4 inhibitors, insulin and RAAS blocking medication was demonstrated." (PMID 31650393, 2020). "In patients with diabetes mellitus, the addition of an inhibitor of dipeptidyl peptidase-4 (DPP-4) to other baseline therapies produced a significant reduction in EAT volume during a 24 w follow-up." (PMID 32024124, 2020). "Dipeptidyl peptidase-4 (DPP-4) inhibitors are used as a treatment for type 2 diabetes mellitus and have also recently been applied to enhance bone quality and density, and increase the expression of bone markers." (PMID 32923485, 2020). "It will provide evidence-based medical evidence for DPP-4 inhibitors in the treatment of diabetes with COVID-19." (PMID 33031311, 2020). "In conclusion, we showed that the DPP-4 inhibitor, linagliptin, improved cognitive dysfunction, at least in part, by decreasing oxidative stress and inhibiting microglial activation in a diabetes model mouse." (PMID 32032367, 2020). "DPP-4 inhibitors, which are used in the treatment of diabetes, appear to reduce macrophage infiltration and insulin resistance but have not been shown to increase the risk of infection in diabetic patients." (PMID 33318519, 2020). "The dipeptidyl peptidase-4 (DPP-4), also known as CD26, is a ubiquitously expressed protease that degrades several substrates, such as incretin hormones and thereby is a therapeutic target in diabetes treatment." (PMID 32823659, 2020). "Inhibitors of dipeptidyl peptidase-4 (DPP-4) are widely used to treat diabetes mellitus, but data concerning their effects on the barrier stability of retinal endothelial cells (REC) in vivo and in vitro are inconsistent." (PMID 32566677, 2020). "This study will explore the effectiveness and safety of DPP-4 inhibitors in the treatment of COVID-19 patients with diabetes." (PMID 33031311, 2020). "Here, in vivo mouse models, DPP4 inhibition was obtained by the administration of Vildagliptin, a substance that is an inhibitor of DPP4 activity commonly used in treating diabetes mellitus type 2." (PMID 33121118, 2020). "DPP-4 inhibitors are capable of simultaneously treating both diabetes and its multiple complications." (PMID 32848788, 2020). "Among them, DPP4 target inhibitors have been widely used in the treatment of diabetes mellitus, which has an important impact on reducing blood sugar in patients." (PMID 32215271, 2020). "There was no significant change in serum creatinine level and creatinine clearance rate in elderly patients with type 2 diabetes mellitus after treatment of DPP-4 inhibitor." (PMID 32368255, 2020). "Numerous studies on both human and animal models showed that circulating DPP4 activity is increased and its inhibition has a potential beneficial effects in diabetes and diabetic disorders." (PMID 31905169, 2020). "The data provide further explanation for the mechanism of the renoprotective effect of SGLT2 inhibitors and DPP4 inhibitors in diabetes." (PMID 32340263, 2020).
diabetes (continued). "Although the benefits promoted by metformin and DPP4 inhibitors on controlling diabetes are well-defined, many investigators have also shown the effects of these drugs beyond glycemia, especially on endothelial function." (PMID 33050169, 2020). "DPP-4 inhibitors are used worldwide to treat type 2 diabetes mellitus and were recently shown to have pleiotropic effects such as anti-oxidant, anti-inflammatory, and anti-fibrotic actions." (PMID 32948146, 2020). "Vildagliptin is a representative of Dipeptidyl Peptidase-4 (DPP-4) inhibitors, antihyperglycemic drugs, approved for use as monotherapy and combination therapy in type 2 diabetes mellitus." (PMID 32218354, 2020). "Dose of other diabetes medications was adjusted according to clinical judgment whereas Dipeptidyl peptidase-4(DPP-4) inhibitors were discontinued." (PMID 32292448, 2020). "DPP4 inhibitors, also commonly called gliptin, are being developed as a class of drugs for treating diabetes." (PMID 33117158, 2020). "Therapy for diabetes included isolated or combined use of metformin, sulfonylureas, and/or dipeptidyl peptidase-4 inhibitors." (PMID 31956343, 2020). "DPP4 inhibitors are used for the treatment of diabetes, but the impact of DPP4 activity and soluble DPP4 on development of diabetes-associated inflammation remains uncertain." (PMID 32724076, 2020). "Given that DPP-4 inhibitors are therapeutic drugs for diabetes that target a part of the CD26 molecule, which is a costimulatory molecule involved in T cell activation, there is concern over their effect on immune mechanisms." (PMID 32337291, 2020). "By 2015, the most commonly initiated second-generation diabetes drugs were DPP-4 inhibitors, but SGLT-2 inhibitors diffused rapidly after their FDA approval in 2013." (PMID 32442290, 2020). "Dipeptidyl peptidase-4 inhibitors (DPP4i) are oral agents used for the pharmacological treatment of adults with type 2 diabetes mellitus (T2DM)." (PMID 32168854, 2020). "Alogliptin, a dipeptidyl peptidase 4 (DPP-4) inhibitor, is clinically used for the treatment of type 2 diabetes mellitus." (PMID 32317735, 2020). "Dipeptidyl peptidase-4 (DPP-4) inhibitors, a class of antidiabetic drugs, have become standard drugs to improve hemoglobin A1c (HbA1c) levels in patients with type 2 diabetes mellitus." (PMID 32539832, 2020). "Simultaneously, a nationwide retrospective observational study that estimated the effect of SGLT2 inhibitors on hHF among diabetes patients suggests that SGLT2 inhibitors reduced hHF compared with dipeptidyl peptidase-4 inhibitors." (PMID 32503541, 2020). "The first oral incretin enhancer, sitagliptin, a selective DPP4 inhibitor, that has been approved for diabetes therapy." (PMID 32430013, 2020). "More than 30% of patients with diabetes were treated with a dipeptidyl peptidase-4 (DPP-4) inhibitor, biguanide, or thiazolidine." (PMID 33373317, 2020). "Soluble DPP4 has also been suggested to be a novel regulator, and elevated levels are indicative of several disorders in addition to diabetes, such as obesity, cardiovascular disease, and nonalcoholic fatty liver disease." (PMID 33117158, 2020). "Recent studies have shown the beneficial effect of dipeptidyl peptidase-4 (DPP4) inhibitor on bone turnover in diabetes mellitus." (PMID 33312197, 2020). "Herein, we investigated the effect of the dipeptidyl peptidase-4 (DPP-4) inhibitor, linagliptin, on diabetes-related cognitive impairment." (PMID 32032367, 2020). "Numerous studies have demonstrated that the risk of developing BP is significantly elevated in individuals who have neurodegenerative diseases or use dipeptidyl peptidase-4 inhibitors (gliptins) to treat diabetes." (PMID 33072118, 2020). "Several clinical trials have addressed the therapeutic strategy of adding dipeptidyl peptidase 4 (DPP-4) inhibitors to the treatment of type 2 diabetes mellitus (DM) inadequately controlled by insulin therapy." (PMID 33224988, 2020).
diabetes (continued). "Recently, DPP-4 inhibitors are commonly used in various individuals with type 2 diabetes mellitus (T2DM) from the young to the elderly because of their good glucose-lowering effect and safety including low risk of hypoglycaemia." (PMID 32337293, 2020). "As a result of this mechanism of action, DPP4 inhibitors (DPP4i) are approved and are used in diabetes mellitus type 2 as monotherapy as well as in combination with metformin." (PMID 32296640, 2020). "Literature data suggests that Dipeptidyl peptidase-4 (DPP-4) is a potential target for type 2 Diabetes Mellitus." (PMID 32884207, 2020). "Dipeptidyl peptidase 4 (DPP-4) inhibitors are widely used as therapeutic agents for diabetes mellitus, reducing serum glucose levels by inhibiting glucagon--like peptide--1(GLP-1) and gastric inhibitory polypeptide (GIP) degradation." (PMID 32489704, 2020). "Recent developments in the pharmacology of diabetes mellitus have led to the discovery of more than one therapeutic drug target to adequately reduce glucose levels and, among these, dipeptidyl peptidase-4 was found to be more effective." (PMID 32075130, 2020). "ACE2 and DPP4 also have established multiple metabolic activities linked to the pharmacologic and physiologic control of cardiovascular and glucose homeostasis and DPP4 inhibitors are used extensively in diabetes therapy." (PMID 33335527, 2020). "Dipeptidyl peptidase-4 (DPP-4) inhibitors are a class of effective hypoglycemic agents for the treatment of type 2 diabetes mellitus (T2DM)." (PMID 32948742, 2020). "DPP-4 inhibitors cannot pass through the blood-brain barrier (BBB) under normal conditions, however, diabetes causes BBB dysfunction." (PMID 32032367, 2020). "The renin–angiotensin–aldosterone system (RAAS) component ACE2 and DPP4 are proteins dysregulated in diabetes." (PMID 32848769, 2020). "Of the 38 (13.1%) patients with diabetes treated with DPP4 inhibitors, 32 (11.07%) were on other oral agents and/or insulin." (PMID 32385343, 2020). "Since teneligliptin is an inhibitor of DPP-4, which is approved for the treatment of diabetes, we examined here the effects of teneligliptin on macrophages under diabetic conditions." (PMID 32646003, 2020). "Regarding medications for diabetes, dipeptidyl peptidase-4 inhibitors were the most common, followed by sulfonylurea." (PMID 30498904, 2019). "Linagliptin is a representative of dipeptidyl peptidase 4 (DPP-4) inhibitors which are registered and used effectively in a treatment of diabetes mellitus type 2." (PMID 31434198, 2019). "The most commonly prescribed diabetes medications were metformin (89.9%), dipeptidyl peptidase-4 inhibitors (61.1%), and sulfonylureas (49.3%)." (PMID 31885556, 2019). "Dipeptidyl peptidase 4 (DPP4) inhibitors, also known as gliptins, are a class of oral hypoglycemic drugs that block the enzyme DPP4 and can be used to treat diabetes mellitus type 2 (DM‐II)." (PMID 31124302, 2019). "Vildagliptin is a dipeptidyl peptidase-IV (DPP-4) inhibitor approved for the treatment of type 2 diabetes mellitus (T2DM)." (PMID 31485457, 2019). "The clinical aspects of the DPP-4 inhibitors, which are now used world-wide for diabetes treatment, will be discussed by Deacon, Ahren and others in other contributors to this Research Topic." (PMID 31080438, 2019). "A consensus report by the American Diabetes Association and the European Association for the Study of Diabetes recommends an incretin-based therapy (GLP-1 analogue or DPP-4 inhibitor) following the failure of metformin monotherapy." (PMID 30813546, 2019). "Evogliptin (EVO) is a potent and selective dipeptidyl peptidase-4 inhibitor (DPP4i) developed for the treatment of type 2 diabetes mellitus (T2DM)." (PMID 31890041, 2019). "In this retrospective study, we attempted to evaluate the association between dipeptidyl peptidase-4 (DPP-4) inhibitors and allergic rhinitis in patients with diabetes." (PMID 31013793, 2019).
diabetes (continued). "We also found that newer diabetes medications (DPP4 inhibitors, GLP-1 receptor agonists, and SGLT2 inhibitors) were all continued in the vast majority of participants initiating insulin." (PMID 30759121, 2019). "The current manuscript will review the mechanism of action, therapeutic utility, and the role of DPP-4 inhibitors for the treatment of type 2 diabetes mellitus." (PMID 31366085, 2019). "The DPP-4 inhibitor is a widely used lower glycemic agent for patients with type 2 diabetes mellitus." (PMID 31664952, 2019). "This study assessed the combined effect of TGR5 agonist and DPP-4 inhibitor on diabetes-based liver fibrosis development." (PMID 31561561, 2019). "Recently several case reports have described BP in patients with diabetes mellitus (DM) patients who have been treated with dipeptidyl peptidase-4 inhibitors (DPP-4i or gliptins), which are a widely used class of anti-DM drugs." (PMID 31275298, 2019). "The dipeptidyl-peptidase-4 (DPP4) inhibitor is a well-known hypoglycemic agent used in patients with type 2 diabetes mellitus." (PMID 31664952, 2019). "Dipeptidyl peptidase 4 (DPP-4) inhibitors are newer oral anti-diabetic agents which have been approved by the Food and Drug Administration for the treatment of patients with type 2 diabetes mellitus (T2DM)." (PMID 30832701, 2019). "We monitored serum amylase level in patients with type 2 diabetes mellitus (T2DM) prescribed either dipeptidyl peptidase-4 inhibitor or GLP-1 analog (GLP-1 group) as monotherapy." (PMID 31727181, 2019). "The GLP-1 was treated with DPP4 inhibitors against diabetes from 2005 to 2007 and still had adverse effects such as rhinopharyngitis and upper respiratory tract infections." (PMID 31652794, 2019). "Glucagon-like peptide-1 is an incretin hormone, and its analogs and dipeptidyl peptidase-4 (DPP4) inhibitors have been widely used for the treatment of type 2 diabetes mellitus (T2DM) recently." (PMID 31779634, 2019). "Peptide vaccine therapy has already been shown to be safe and useful in the fields of hypertension and diabetes, targeting angiotensin II (AngII) and dipeptidyl peptidase-4 (DPP4), respectively." (PMID 30846754, 2019). "Sitagliptin is an inhibitor of the enzyme dipeptidyl peptidase-4, used for the treatment of type 2 diabetes mellitus." (PMID 31344887, 2019). "Dipeptidyl peptidase-4 (DPP-4) is a well-known therapeutic drug target proven to reduce blood glucose levels in diabetes mellitus, and clinically, DPP-4 inhibitors are used in combination with other anti-diabetic agents." (PMID 30862104, 2019). "The incretin-based medicines GLP1 analogues (GLP1a) and dipeptidyl peptidase-4 inhibitors (DPP4i) are hypoglycaemic agents licensed for the treatment of type 2 diabetes mellitus (T2DM)." (PMID 30732592, 2019). "As one of the strategies in the management of diabetes consists of the inhibition of the DPP-4 activity, it is particularly interesting to investigate the relevance of the DPP-4 activities produced by the gut microbes." (PMID 30186247, 2018). "Several clinical studies have reported the application of dipeptidyl peptidase-4 (DPP-4) inhibitors as treatments for type 1 diabetes mellitus (T1DM)." (PMID 29507862, 2018). "DPP4 inhibition is an established therapeutic approach for diabetes, and PM slightly (p < 0.1) suppressed FBG elevation in our mice study." (PMID 30279329, 2018). "In a country with low penetration of DPP-4 inhibitors (eg, Hong Kong), users had diabetes with multiple comorbid conditions compared with biguanidine users." (PMID 30540837, 2018). "Dipeptidyl peptidase-4 (DPP-4) inhibitors, which have been widely used as outstanding blood glucose-dependent antidiabetic agents for patients with type 2 diabetes mellitus (T2DM), show promise." (PMID 29507862, 2018). "In the context of diabetes, DPP4 inhibitors have been described as having many effects including antioxidant effects." (PMID 29979777, 2018).